ANG (angiogenin)
Diseases named in the same sentence as ANG in open-access papers (continued):
Sharing a sentence is not in itself a finding about the gene and the disease.
melanoma (10 papers, 2003 to 2024). A malignant, usually aggressive tumor composed of atypical, neoplastic melanocytes. "Solid‐state antibody chip results, including 105 antibodies, showed that GC‐7 and GL‐1 affected the expression of melanoma cytokines, among which ANG, IGFBP3, CSF2, CD71, CXCL1, and MMP9 were the most significant." (PMID 38952061, 2024). "As such, angiogenin is thought by some to represent an autocrine growth factor in malignant melanoma of the skin, and has been reported to predict treatment response in patients with metastatic cutaneous melanoma." (PMID 27878431, 2017). "These indicated that angiogenin is the most potent angiogenic factor in melanomas." (PMID 12610518, 2003). "Thus, angiogenin may have an important role in melanoma-related angiogenesis and may represent an important target of anti-angiogenic therapy." (PMID 27878431, 2017). "According to these results, we concluded that serum ANG levels are upregulated in patients with cancer, especially patients with CRC, AML, MM, melanoma, and MDSs." (PMID 29736193, 2018). "Aqueous humor levels of angiogenin, IL-8, and MCP-1 were significantly higher in eyes with malignant melanoma than in those with benign tumors (p < 0.05)." (PMID 27878431, 2017). "hrRNASET2 also induced full arrest of angiogenin-induced tube formation and brought to a three-fold lower relative HT29 colorectal and A375SM melanoma tumor volume, when compared to Avastin-treated animals." (PMID 27014725, 2016). "Angiogenin production was reported to be upregulated in melanoma cell lines but not in normal melanocytes under hypoxic condition." (PMID 12610518, 2003). "In fact, we found a significant correlation between the number of CD3-positive cells/mm2 in melanoma specimens and aqueous MCP-1 (R2 = 0.47, p = 0.01) as well as IL-8 levels (R2 = 0.63, p = 0.0011), but not angiogenin level (R2 = 0.007, p = 0.78) (data not shown)." (PMID 27878431, 2017).
metabolic syndrome (10 papers, 2015 to 2024). A cluster of metabolic risk factors for CARDIOVASCULAR DISEASES and TYPE 2 DIABETES MELLITUS. "Our report is dedicated to the hypothesis that the presence of metabolic syndrome is associated with increased angiogenin concentration and cIMT." (PMID 37761032, 2023). "In our study, we analyzed the effect of metabolic syndrome on the relationship between angiogenin levels and cIMT in patients with type 1 diabetes." (PMID 37761032, 2023). "Angiogenin levels were significantly higher in the control group compared to the study group, even after excluding patients with metabolic syndrome, those treated with medications, and active smokers." (PMID 37761032, 2023). "Little is known about angiogenin levels as a marker of subclinical macrovascular complications in adult patients with type 1 diabetes and concomitant metabolic syndrome." (PMID 37761032, 2023). "Our present study revealed that angiogenin levels were significantly higher in the control group compared to the diabetic group, even after excluding patients with metabolic syndrome, those taking medications, and smokers." (PMID 37761032, 2023). "Therefore, we decided to study the influence of metabolic syndrome on the relationship between angiogenin concentration and intima-media thickness (cIMT) in patients with type 1 diabetes." (PMID 37761032, 2023). "However, the presence of concomitant metabolic syndrome in these patients was noted in angiogenin levels." (PMID 37761032, 2023). "However, little is known about angiogenin levels and subclinical macrovascular organ damage in patients with DM1 and concomitant metabolic syndrome (MS)." (PMID 37761032, 2023). "In summary, it can be concluded that metabolic syndrome in patients with type 1 diabetes does not appear to impact angiogenin levels or cIMT." (PMID 37761032, 2023). "Additionally, discussion of the results we have obtained was somewhat difficult due to the lack of other reports on angiogenin and cIMT in patients with metabolic syndrome and type 1 diabetes." (PMID 37761032, 2023).
pancreatic cancer (10 papers, 2005 to 2026). "On the other hand, PLAU interacted directly with one negatively correlated gene, ANG (angiogenin), the high expression of which is reported to be favourable in pancreatic cancer." (PMID 36591282, 2022). "EGFR is the common cell surface receptor of RNase A and angiogenin to trigger proliferation of pancreatic cancer cells." (PMID 30534052, 2018). "An oncogenic role of hRNase5/ANG in pancreatic cancer through activation EGFR phosphorylation rendered cancer cells more addicted to the EGFR pathway and sensitive to EGFR TKI erlotinib treatment in vitro and in vivo." (PMID 30449278, 2018). "In pancreatic cancer cells, hRNase5/ANG expression is critically driven by the PTEN/PI3K/Akt activating pathway." (PMID 30449278, 2018). "Previously, elevated serum level of hRNase5/ANG was shown to correlate with poorer patient survival in pancreatic cancer." (PMID 30449278, 2018). "Increased levels of hRNase5/ANG were reported to correlate with pancreatic cancer occurrence and aggressiveness." (PMID 30449278, 2018). "A new and timely report (see next section) provides insights into the potential of hRNase5/ANG serving as a non-invasive serum biomarker to stratify pancreatic cancer patients for erlotinib therapy." (PMID 30449278, 2018). "The increased hRNase5/ANG mRNA expression is also found in pancreatic acinar cells and interstitial fibroblasts in the tissues surrounding pancreatic cancer." (PMID 30449278, 2018). "It would be worthwhile to further evaluate hRNase5/ANG as a predictive biomarker for EGFR inhibitor therapy in pancreatic cancer in a systematic way through prospective clinical trials in the future." (PMID 30449278, 2018). "Moreover, a positive correlation between hRNase5/ANG and EGFR activation was observed in human pancreatic tissue microarrays, supporting the pathological relevance of the hRNase5/ANG-EGFR relationship in pancreatic cancer." (PMID 30449278, 2018). "Notably, hRNase5/ANG, whose level in sera of pancreatic cancer patients, serves as a non-invasive serum biomarker to stratify patients for predicting the sensitivity to EGFR-targeted therapy." (PMID 30449278, 2018). "Moreover, high plasma hRNase5/ANG level of pancreatic cancer patients can predict better treatment response to erlotinib with the potential to serve as a serum biomarker to stratify patients for erlotinib treatment." (PMID 30449278, 2018). "In addition to P19 cells, angiogenin and RNase A also trigger cell proliferation of various pancreatic cancer cells via the EGFR-ERK pathway." (PMID 30534052, 2018). "Besides pancreatic cancer, whether this oncogenic addiction through activation of the hRNase5/ANG-EGFR axis exists in other tumor types remains to be determined." (PMID 30449278, 2018). "And recent studies reported angiogenin is a new EGFR ligand and contribute to pancreatic cancer progression." (PMID 39838173, 2025). "A very recent study showed that RNase A and angiogenin activate the EGFR-ERK pathway and AKT to promote proliferation of pancreatic cancer cells." (PMID 30534052, 2018). "It would be of interest to further address the regulatory mechanisms and functions of hRNase5/ANG and EGFR, either autocrine or paracrine in different cells in the pancreatic tumor microenvironment." (PMID 30449278, 2018). "Numerous angiogenic factors are overexpressed in pancreatic cancer, including vascular endothelial growth factor (VEGF), bFGF, and angiogenin, as well as members of the TGF-β, and FGF gene families." (PMID 15710044, 2005). "For instance, in pancreatic cancer, the upregulation of tRF‐Pro‐AGG‐004 and tRF‐Leu‐CAG‐002 might result from increased angiogenin (ANG), a nucleic acid endonuclease." (PMID 39993386, 2025). "Finally, considering hRNase5/ANG as a predictive biomarker in pancreatic cancer, a subset of patients with hRNase5/ANGhigh-EGFR+ population (around 30% based on plasma hRNase5/ANG estimation) may benefit from erlotinib treatment." (PMID 30449278, 2018).
pancreatic cancer (continued). "Second, whether the interplay between hRNase5/ANG and EGFR identified in pancreatic cancer also contributes to the signaling modulation in the pancreatic tumor microenvironment where a dense stromal matrix, including endothelial cells and fibroblasts, is a prominent histopathological hallmark." (PMID 30449278, 2018). "Most recently, Hung and colleagues identified hRNase5/ANG as an EGFR ligand to induce its binding to EGFR and activate EGFR signaling in an RNase catalytic-independent manner, which highlights an oncogenic role of the hRNase5/ANG-EGFR axis in pancreatic cancer." (PMID 30449278, 2018).
glioblastoma (9 papers, 2017 to 2023). The most malignant astrocytic tumor (WHO grade IV). "ANG, angiogenin, is a multifunctional secreted ribonuclease that is upregulated in human glioblastoma that promotes glioblastoma progression by enhancing invasion, vascular association, proliferation, and survival." (PMID 37891828, 2023). "Recently, serum ANG level has been found to be a prognostic factor for numerous tumours, such as glioblastoma, non-Hodgkin lymphoma, cervical cancer, and laryngeal carcinoma." (PMID 34512316, 2021). "LSM imaging of intracellular angiogenin in glioblastoma and differentiated neuroblastoma cells confirmed the western blot results that untreated non-tumour d-SHSY5Y cells showed lower levels of endogenous ANG in the cytoplasm and in the nucleus than untreated tumour A172 cells." (PMID 31500197, 2019). "Analysis of exosomes from glioblastoma cells showed that they are enriched with the proangiogenic factors VEGF, angiogenin, TGFβ, IL-8, IL-6, MMP2, MMP9, TIMP-1, TIMP-2, and CXCR4." (PMID 35740619, 2022). "Glioblastoma-derived MVs contain VEGF, angiogenin, IL-8, PDGF, and miRNA-19b, and it has been shown that VEGF and angiogenin bind to the cognate receptor on the surface of ECs and promote angiogenesis." (PMID 28730141, 2017). "Moreover, we scored individual cancer cells in multiple regions of the glioblastoma tumors (n = 1,000 cells/tumor; n = 10 of each glioblastoma subtype) and generated coexpression maps of YKL-40 and VEGF/ANG." (PMID 28744448, 2017).
Hepatic fibrosis (9 papers, 2015 to 2024). The presence of excessive fibrous connective tissue in the liver. "In a three-way ANOVA analysis, liver steatosis was linked with the kinetics of EGF, VEGF and ANG, while liver fibrosis was not a source of variation in our analysis." (PMID 39200991, 2024).
viral infection (9 papers, 2015 to 2025). "tsRNAs originate from ncRNAs generated by ribonucleases (RNases) such as angiogenin (ANG) or Dicer under stress conditions (hypoxia, starvation, viral infection, arsenite, heat shock, or heavy metal-induced cellular stress/toxicity conditions)." (PMID 40726981, 2025). "Apart from the eosinophil-derived proteins, angiogenin (ANG/RNase 5) may play a role during viral infection." (PMID 33660566, 2021). "Next, to confirm whether IFNβ overproduction during viral infection is a common phenomenon in all ALS patients, we examined IFNβ production by cells from several ALS patients with mutations in the ALS-causative genes, SOD1, FUS, ANG, FIG4, and TARDBP." (PMID 37352136, 2023). "Members of the RNase A superfamily can also produce tRNA halves in the absence of ANG, whereas RNase L produces tRNA halves from specific tRNAs in response to viral infection." (PMID 37987365, 2023).
colitis (8 papers, 2017 to 2025). Inflammation of the colon. "Utilizing the AOM-DSS mouse model of colitis-associated cancer, the present study suggests that angiogenin-1 and angiogenin-4affect the response to both acute and chronic colitis as well as the development of colitis-associated cancer." (PMID 36881568, 2023). "Important questions remain regarding how angiogenin contributes to both the counter-regulatory response to colitis and the development of colitis-associated cancer." (PMID 36881568, 2023). "Taken together, these findings suggest that angiogenin subtypes may play an important role in the counter-regulatory response to colitis and the development of colitis-associated cancer." (PMID 36881568, 2023). "We hypothesize that these durable effects may be the mechanism by which angiogenin regulates chronic colitis as well as colitis-associated cancer." (PMID 36881568, 2023). "Here we show that ANG expression is up-regulated in macrophages during colitis treatment or upon lipopolysaccharides (LPS) treatment." (PMID 38567413, 2024). "This discordance between the severity of colitis and the development of cancer was surprising and suggests that angiogenin-specific alterations in the colonic microenvironment play an important mechanistic role." (PMID 36881568, 2023). "A growing body of evidence supports the concept that angiogenin is dynamically regulated in colitis." (PMID 36881568, 2023). "Furthermore, the therapeutic potential of recombinant ANG has been demonstrated in a mouse model of colitis." (PMID 38567413, 2024). "Human patients with active IBD have been noted to have elevated serum levels of angiogenin, and we and others have found that angiogenin expression is not only altered in the setting of colitis, but is a key modulator of the physiologic responses of the GI microenvironment to inflammation." (PMID 36881568, 2023). "However, the impact of angiogenin on chronic colitis and the development of colitis-associated cancer has not been previously studied." (PMID 36881568, 2023). "While other groups have reported that fecal angiogenin levels are reduced in the setting of murine colitis, angiogenin-4 levels within colon tissue have not been previously reported." (PMID 36881568, 2023). "Most notably, we found that the difference in colitis severity was even more pronounced during the recovery phases of each cycle of DSS-induced colitis (P<0.05), suggesting that angiogenin may be most relevant during the reparative processes that follow acute injury." (PMID 36881568, 2023).
Hyperglycemia (8 papers, 2014 to 2025). An increased concentration of glucose in the blood. "Persistent hyperglycemia results in retinal damage through oxidative stress and hypoxia, prompting the transcription of ANG, a member of the RNase A family." (PMID 39513253, 2025). "Hyperglycemia impairs neovascularization in diabetic wounds by suppressing key angiogenic factors, including angiogenin (ANG) and VEGF." (PMID 40422838, 2025). "Moreover, decreased Na:K is suggestive of increased aldosterone activity and supports fact that persistent hyperglycemia stimulates the ANG and renin expression in tubular and mesangial cells." (PMID 33170841, 2020).
colon carcinoma (7 papers, 2014 to 2024). "Increasing Angiopoietin-2 and its receptor Tie-2 induces early induction of pro-inflammatory factors related to the development of colon cancer, and an increase in angiogenin was found to be correlated with tumor vascularization." (PMID 32984039, 2020). "Our study shows that glucocorticoids reduced prostanoids, urokinase-type plasminogen activator (uPA) and angiopoietin-like protein-2 (ANGPTL2) levels, but increased angiogenin (ANG) in supernatant from human CT5.3hTERT colon cancer-derived myofibroblasts." (PMID 27717848, 2017). "Angiogenin has been first isolated from supernatants of colon carcinoma cells on its property to induce angiogenesis in chicken chorioallantoic membrane." (PMID 25093183, 2014). "We have described the expression of angiogenin, in NK from patients with colon cancer." (PMID 31057536, 2019).
coronary artery disease (7 papers, 2013 to 2024). "Other proteins associated with incident HF in our research have been linked to coronary heart disease (ANG, C1QTNF1 and CCL3) and thromboembolism (SERPINA5) with the potential to induce myocardial damage." (PMID 35945262, 2022). "Previously, it was reported that plasma angiogenin levels are higher in patients with chronic heart failure and coronary artery disease than in healthy controls in cross-sectional studies." (PMID 38360721, 2024). "The amount of PGE2, TSG-6, bFGF and Angiogenin secreted from MSCs cultured with Cellhesion® MS is higher than in MSCs in monolayer culture, indicating that a Cellhesion® MS culture is more efficient in producing cells to treat diseases such as ischemic heart disease and cartilage injury." (PMID 35326446, 2022). "A follow-up study were performed in 203 patients with coronary heart failure (CHF), 413 coronary heart disease patients without chronic heart failure (also called CHD disease controls), and 53 healthy controls to explore the potential utility of ANG as a biomarker." (PMID 33041815, 2020).
endometriosis (7 papers, 2013 to 2025). The growth of functional endometrial tissue in anatomic sites outside the uterine body. "Numerous studies have reported elevated ANG levels in the serum and/or peritoneal fluid of endometriosis patients compared to controls." (PMID 40072086, 2025). "Endometriosis patients show elevated levels of different pro-angiogenic factors including IL-8, IL-6, angiogenin, HGF and prostaglandin E2." (PMID 27695098, 2016). "In addition, previous studies have shown that serum ANG levels are also elevated in women with endometriosis, as well as women with severe ovarian hyperstimulation syndrome (OHSS), compared with those in healthy controls." (PMID 29736193, 2018). "Increased ANG, VEGFA, and sVEGFR-1 expression was previously observed in the peritoneal fluid of women with endometriosis." (PMID 38069001, 2023). "The levels of angiogenin, CD105, ICAM-1, CXCL10, leptin, lipocalin-2, MMP-9, osteopontin, RBP4, PAI-1, ABP, CD31, TIM-2, and VCAM-1 were higher in the endometriosis group than in the control group." (PMID 34072419, 2021). "In healthy controls, ANG expression increased between proliferative and secretory phases, aligning with the implantation window, whereas this pattern was absent in endometriosis patients." (PMID 40072086, 2025). "Additionally, estrogens and hypoxia-related factors [angiogenin (ANG), angiopoietin 1 (ANGPT1), or vascular endothelial growth factor (VEGF)] have been suggested to promote endometriosis-related EMT via MAPK/ERK, PI3K/AKT, or β-catenin cascades." (PMID 38674005, 2024). "Other proangiogenic factors, namely, IL-8, hepatocyte growth factor (HGF), erythropoietin, angiogenin, macrophage migration inhibitory factor, neutrophil-activating factor, and TNF-α, are all found at increased concentrations in the peritoneal fluid of patients with endometriosis." (PMID 23766765, 2013).